NDUFA1 (NADH:ubiquinone oxidoreductase subunit A1)
Description:
Accessory subunit of the mitochondrial membrane respiratory chain NADH dehydrogenase (Complex I), that is believed not to be involved in catalysis. Complex I functions in the transfer of electrons from NADH to the respiratory chain. The immediate electron acceptor for the enzyme is believed to be ubiquinone.
Synonyms: CI-MWFE; MWFE; MC1DN12; ZNF183
Tractability: Small molecule: an approved drug acts on it; a structure with a bound ligand is known. Antibody: UniProt predicts a signal peptide or a membrane-spanning region. PROTAC: ubiquitination databases record sites on it.
Gene: Protein-coding gene on chromosome X (119,871,796 to 119,876,689, forward strand). Ensembl gene ENSG00000125356.
Subcellular location: Mitochondrion inner membrane
Subcellular location (Human Protein Atlas): Cytosol; Mitochondria
Pathways (Reactome):
Metabolism: Complex I biogenesis; Respiratory electron transport
Gene Ontology:
Molecular function: NADH dehydrogenase (ubiquinone) activity
Biological process: aerobic respiration; mitochondrial electron transport, NADH to ubiquinone; proton motive force-driven mitochondrial ATP synthesis; proton transmembrane transport
Cellular component: mitochondrial inner membrane; mitochondrial membrane; mitochondrion; respiratory chain complex I
Gene-disease validity (ClinGen):
ClinGen rates the evidence that NDUFA1 causes each of these diseases.
Leigh syndrome (X-linked): Moderate. A progressive neurological disease defined by specific neuropathological features associating brainstem and basal ganglia lesions.
mitochondrial disease (X-linked): Moderate.
Homologues: Orthologues: chimpanzee NDUFA1 (99% identical), macaque NDUFA1 (90% identical), mouse Ndufa1 (83% identical), dog NDUFA1 (81% identical), pig NDUFA1 (79% identical), rat Ndufa1 (74% identical), zebrafish ndufa1 (66% identical), tropical clawed frog ndufa1 (60% identical), Drosophila melanogaster ND-MWFE (31% identical).
Diseases named in the same sentence as NDUFA1 in open-access papers:
NDUFA1 is named in the same sentence as 49 diseases in open-access papers, as found by Europe PMC text mining. Sharing a sentence is not in itself a finding about the gene and the disease. The quoted sentences say what the papers report.
Alzheimer disease (6 papers, 2016 to 2024). A progressive, neurodegenerative disease characterized by loss of function and death of nerve cells in several areas of the brain leading to loss of cognitive function such as memory and language. "The down-regulated DEGs in NM versus NN were primarily focused on ribosome (about 26 DEGs, including RPL37A and RPL35), Alzheimer’s disease (about 20 DEGs, including SNCA and COX8A), and retrograde endocannabinoid signaling (about 6 DEGs, such as NDUFA1 and GNG5)." (PMID 38660519, 2024).
Huntington disease (6 papers, 2016 to 2021). Huntington disease (HD) is a rare neurodegenerative disorder of the central nervous system characterized by unwanted choreatic movements, behavioral and psychiatric disturbances and dementia. "Dysregulation resulting from missense mutation in NDUFA1 contributes to Parkinson’s, Alzheimer’s and Huntington’s diseases." (PMID 29249826, 2017). "NDUFA1 expression has also been associated with Parkinson’s disease, AD and Huntington’s disease." (PMID 33466931, 2021).
Parkinson disease (6 papers, 2011 to 2021). A progressive degenerative disorder of the central nervous system characterized by loss of dopamine producing neurons in the substantia nigra and the presence of Lewy bodies in the substantia nigra and locus coeruleus. "Second, and more interesting, the oxidative phosphorylation chain, including seven genes (ATP5C1, ATP6AP1, ATP6V1H, COX5B, COX6B1, NDUFA1, and UQCRC1), five of them shared with Huntington's and Parkinson's disease KEGG categories." (PMID 21541025, 2011).
breast cancer (3 papers, 2019 to 2024). A primary or metastatic malignant neoplasm involving the breast. "To further verify the identified target genes that showed significant changes in DE and DM patterns in response to the combination treatment, we evaluated the expression of Pdx1, Tmem132d, Get4, Rpl13 and Ndufa1 genes in mouse mammary tumors using qRT-PCR." (PMID 33947955, 2021).
Sepsis (3 papers, 2021 to 2025). Sepsis is defined as life-threatening organ dysfunction caused by a dysregulated host response to infection. "Macrophage differentiation trajectories revealed increased expression of BLOC1S1 and NDUFA1 during later stages of sepsis, suggesting their involvement in immune cell reprogramming." (PMID 40370519, 2025). "Clinically, BLOC1S1, NDUFA1, and SFT2D1—have also been implicated in various disease contexts beyond sepsis." (PMID 40370519, 2025). "NDUFA1, a component of mitochondrial complex I, plays a pivotal role in electron transport and energy production, highlighting its involvement in sepsis-related metabolic dysregulation." (PMID 40370519, 2025). "This study identified three histone acetylation-related genes, BLOC1S1, NDUFA1, and SFT2D1, as potential biomarkers for sepsis through integrated bioinformatics analysis." (PMID 40370519, 2025). "This study identified BLOC1S1, NDUFA1, and SFT2D1 as histone acetylation-related biomarkers for sepsis and validated their expression in THP-1 cell models and patient blood samples." (PMID 40370519, 2025). "Furthermore, validation using patient blood samples confirmed the elevated expression levels of BLOC1S1, NDUFA1, and SFT2D1 in sepsis patients compared to healthy controls." (PMID 40370519, 2025). "Although sepsis-AKI led to reduced mtDNA levels and integrity, it did not affect mRNA expression of mitochondrial genes encoding key components of the mitochondrial electron transport chain complexes (i.e., ND1, ND4, COX1, CYTB, COX5b and NDUFA1)." (PMID 33494815, 2021).
basal cell carcinoma (2 papers, 2021 to 2024). A carcinoma involving the basal cells. "Downregulation or loss of NDUFA1 expression is a known consistent feature of basal cell carcinoma, while reduced expression of IL13RA1 has been associated with apoptosis and promotion of epithelial to mesenchymal transition (EMT) in pancreatic cancer." (PMID 38694815, 2024). "And the downregulation of NDUFA1 was correlated with basal cell carcinoma." (PMID 34692528, 2021).
coronary artery disease (2 papers, 2024). "NDUFB8 and NDUFA1 are known from patients with coronary artery disease (CAD)." (PMID 38396938, 2024). "Exercise can also induce the expression of NDUFA1 and CASP3, which are used to predict the respiratory chain component in patients with coronary artery disease." (PMID 38963098, 2024). "Other downregulated genes, such as NDUFA1 and NDUFB8, are related to coronary artery disease." (PMID 38396938, 2024).
Cognitive impairment (1 paper, 2025). Abnormal cognition is characterized by deficits in thinking, reasoning, or remembering. "To further verify the effects of Ndufa1 on Hcy-induced cognitive impairment in rats, we constructed an adeno-associated virus (AAV-Vector and AAV-Ndufa1) and injected into the hippocampus of the rats before Hcy tail injection." (PMID 40624018, 2025). "In general, these findings suggested that the upregulation of Ndufa1 effectively mitigated Hcy-induced cognitive impairment in the hippocampus of rats." (PMID 40624018, 2025). "Based on Ndufa1 is related to mitochondrial function and the importance of mitochondrial function for nerve cells, we investigated the effects of the upregulation of Ndufa1 on cognitive impairment in Hcy-treated rats." (PMID 40624018, 2025). "However, the mechanism of Ndufa1 reduction and the role of Ndufa1 in cognitive impairment are unclear." (PMID 40624018, 2025). "Importantly, systematic analysis of differentially expressed genes between AD patients and controls indicated that Ndufa1 could be used as a predictive candidate biomarker for mild cognitive impairment (MCI) and AD." (PMID 40624018, 2025). "Recently, the least absolute shrinkage and selection operator (LASSO) and support vector machine recursive feature elimination (SVM-RFE) analyses identified Ndufa1 as a candidate gene for predicting late-onset AD (LOAD) and mild cognitive impairment (MCI)." (PMID 40624018, 2025). "Ndufa1 upregulation or NAD+ supplement can normalize Hcy-induced mitochondrial homeostasis defects and cognitive impairment." (PMID 40624018, 2025). "Our findings suggested that Hcy interfered with mitochondrial homeostasis by inhibiting NAD+ metabolism via Ndufa1 in the chronic course of neurodegeneration and that NAD+ supplementation could ameliorate Hcy-induced neurodegeneration and cognitive impairment." (PMID 40624018, 2025). "Thus, Ndufa1 is a key molecular switch of Hcy-induced mitochondrial damage, and targeting Ndufa1 or NAD+ replenishment appropriately can ameliorate Hcy-induced neurodegeneration and cognitive impairment." (PMID 40624018, 2025). "Thus, Ndufa1 is a key molecular switch of Hcy-induced mitochondrial damage, and appropriately targeting Ndufa1 or NAD+ replenishment may serve as a novel therapeutic strategy for Hcy-induced neurodegeneration and cognitive impairment." (PMID 40624018, 2025).
dementia (1 paper, 2023). Loss of intellectual abilities interfering with an individual's social and occupational functions. "Gly32Arg SNP is a mutational site in NDUFA1 Reported that may be associated with early-onset dementia." (PMID 37545529, 2023).
epilepsy (1 paper, 2023). A brain disorder characterized by episodes of abnormally increased neuronal discharge resulting in transient episodes of sensory or motor neurological dysfunction, or psychic dysfunction. "ATP5ME and NDUFA1 showed higher expression in blood RNA of the TSC epilepsy group compared with the other two groups, and encode mitochondrial components important for mitochondrial energy production." (PMID 37996417, 2023).
esophageal cancer (1 paper, 2021). A primary or metastatic malignant neoplasm involving the esophagus. "NDUFA1 depletion resulted in decreases of proliferation, anchorage-independent growth, and colony formation in esophageal cancer cell lines, indicating that NDUFA1 plays an important role in cancer cell proliferation." (PMID 34226508, 2021). "In this study, we found that the proliferation and clone formation of esophageal cancer cells were significantly inhibited after NDUFA1 depleted." (PMID 34226508, 2021). "We also observed that NDUFA1 expression is elevated in esophageal cancer, and lower NDUFA1 expression is correlated with better patient prognosis." (PMID 34226508, 2021). "Using The Cancer Genome Atlas database, we analyzed the relationships of NDUFA1, NDUFS5, and COX6B1 expression with esophageal cancer." (PMID 34226508, 2021).
glioblastoma (1 paper, 2023). The most malignant astrocytic tumor (WHO grade IV). "This is consistent with a previous report that showed that GO attenuates the expression of genes associated with the oxidative phosphorylation complexes, such as NDUFA1, NDUFB3, and NDUFS4 in glioblastoma U87 cell line." (PMID 36839713, 2023).
glioma (1 paper, 2021). A benign or malignant brain and spinal cord tumor that arises from glial cells (astrocytes, oligodendrocytes, ependymal cells). "In addition, we found that four of the candidate tumor gene biomarkers (NDUFS5, NDUFA1, NDUFA13, and NDUFB8) belong to the NADH ubiquinone oxidoreductase subunit gene family, so we inferred that this gene family may be strongly related to glioma." (PMID 34863158, 2021).
head and neck squamous cell carcinoma (1 paper, 2023). A squamous cell carcinoma that arises from any of the following anatomic sites: lip and oral cavity, nasal cavity, paranasal sinuses, pharynx, larynx, and salivary glands. "NDUFA1, subunit of mitochondrial complex I, was associated with the prognosis of head and neck squamous cell carcinoma." (PMID 37138869, 2023).
heart failure (1 paper, 2024). Inability of the heart to pump blood at an adequate rate to meet tissue metabolic requirements. "We could show that genes important for ATP biosynthesis and electron transport (e.g., PGAM2, NDUFA1, and TMEM126A) are consistently downregulated in heart failure." (PMID 38573186, 2024).
hereditary optic neuropathy (1 paper, 2025). "The Ndufa1 gene and mitochondrial DNA mutations are associated with hereditary optic neuropathy in Leber, while its pathophysiology is still poorly understood." (PMID 40271076, 2025).
melanoma (1 paper, 2023). A malignant, usually aggressive tumor composed of atypical, neoplastic melanocytes. "In summary, these results provide evidence supporting a role of Psmc3 and Ndufa1 in the susceptibility of melanoma cells to CTL‐mediated killing." (PMID 36718025, 2023).
mesothelioma (1 paper, 2024). A usually malignant and aggressive neoplasm of the mesothelium which is often associated with exposure to asbestos. "We note that the increased expression of NDUFA1, TES and IL13RA1 associated with poor survival outcome in the TCGA mesothelioma cohort contrasted with the literature." (PMID 38694815, 2024).
mitochondrial encephalomyopathy (1 paper, 2025). A heterogenous group of disorders characterized by alterations of mitochondrial metabolism that result in muscle and nervous system dysfunction. "For example, several X-linked mutations associated with Complex I dysfunction have been characterized by various pathologies, including the NDUFA1 gene implicated in mitochondrial encephalomyopathy." (PMID 40592454, 2025).
Optic neuropathy (1 paper, 2012). "Since there was no way to introduce DNA directly into the mitochondria of a live animal, we had previously knocked down expression of a critical nuclear-encoded complex I subunit, NADH ubiquinone oxidoreductase subunit NDUFA1 (NDUFA1), to induce optic neuropathy in the mouse." (PMID 22773905, 2012).
ovarian carcinoma (1 paper, 2024). A malignant neoplasm originating from the surface ovarian epithelium. "The results presented in this manuscript reveal that the treatment of ovarian cancer cells with RuCN induced a higher content of α-helices and a lower content of β-sheet structures compared to the untreated control and the overexpression of NDUFA1 and NDUFB5, respectively." (PMID 39204341, 2024).
Stroke (1 paper, 2024). Sudden impairment of blood flow to a part of the brain due to occlusion or rupture of an artery to the brain. "Core genes (UQCRQ, USMG5 [ATP5MD], COX6C, NDUFB3, ATP5L [ATP5MG], COX7C, NDUFA1, NDUFA4) were highly expressed in septic shock and stroke samples." (PMID 39655053, 2024).
tumor (7 papers, 2007 to 2025). "NDUFA1, a component of mitochondrial complex I, has similarly been linked to neurodegenerative diseases and multiple tumor types, reflecting its central role in energy metabolism." (PMID 40370519, 2025). "The results indicated that cloperastine inhibited tumor growth was by suppressing NDUFA1, NDUFS5, and COX6B1 expression." (PMID 34226508, 2021). "As a component of complex I, NDUFA1 is essential for respiratory activity and tumor growth." (PMID 34579723, 2021). "Potent tumour suppressors (e.g. PTEN), cell cycle mediators (e.g. CCND1), and cellular respiration genes (e.g. NDUFA1) were found to be tightly regulated in the normal libraries." (PMID 17543121, 2007). "In addition, we found that four (NDUFS5, NDUFA1, NDUFA13, and NDUFB8) of the candidate tumor gene biomarkers belong to the NADH ubiquinone oxidoreductase subunit gene family." (PMID 34863158, 2021).
cancer (5 papers, 2021 to 2024). A tumor composed of atypical neoplastic, often pleomorphic cells that invade other tissues. "Additionally, COX7B, IARS2, COA3 and NDUFA1 were associated with platinum resistance, cancer cell proliferation and invasion, highlighting their significance as potential therapeutic targets and prognostic biomarkers." (PMID 38534098, 2024). "In addation, CAT, POLE, NTHL1, ATP7B, ISCA2, NDUFA1 and NDUFB2 have also been reported to play a key role in the development of cancers." (PMID 36685880, 2022).
infection (3 papers, 2020 to 2023). The state of being infected such as from the introduction of a foreign agent such as serum, vaccine, antigenic substance or organism. "Regarding the oxidative phosphorylation genes analyzed, Ndufa1 and ATP6v1b2 displayed the reported kinetics, characterized by an initial decrease of expression during days 3 and 4 post infection, followed by an increase during the recovery phase." (PMID 37679643, 2023).
heart disease (1 paper, 2024). "PGAM2 and NDUFA1 have been described in the context of heart disease in mice and rats, respectively, but their role in humans is unknown." (PMID 38573186, 2024).
NDUFA1 also shares sentences with these, for which no sentence is quoted: lactic acidosis (2 papers); Leigh syndrome (2); acute kidney injury (1); airway hyperresponsiveness (1); cerebellar ataxia (1); cervical cancer (1); COVID-19 (1); Dystonia (1); Encephalopathy (1); hyperhomocysteinemia (1); inflammation (1); influenza infection (1); lung adenocarcinoma (1); lung carcinoma (1); MELAS (1); microcephaly (1); mitochondrial disease (1); myopathy (1); neurodegenerative disease (1); non-alcoholic fatty liver disease (1); optic atrophy (1); pancreatic cancer (1); Parkinson’s (1).